STAT1 (signal transducer and activator of transcription 1)
Diseases named in the same sentence as STAT1 in open-access papers (continued):
Sharing a sentence is not in itself a finding about the gene and the disease.
liver cancer (continued). "Thus, our data in liver cancer cell lines are in line with previous studies in fibroblasts and ma-crophages whereby a disbalance between STAT1 and STAT3 may lead to the activation of IFN-γ/STAT1 target genes in a proinflammatory IL-6-containing tumor microenvironment." (PMID 35267462, 2022). "This study focused on the role of STAT1 and STAT3 signaling in liver cancer." (PMID 35267462, 2022). "However, the interplay between STAT1 and STAT3 signaling in liver cancer cells and the immune cell composition regarding STAT1 and STAT3 expression in the tumor cells is still unclear." (PMID 35267462, 2022). "Furthermore, tyrosine kinase inhibitors (TKIs), such as regorafenib, have been shown to enhance tumor antigen presentation and stimulate antitumor immunity through the activation and phosphorylation of STAT1 by IFN-γ, promoting HLA-I expression in liver cancer cells." (PMID 40909948, 2025). "Therefore, we did not observe any significant effect of STAT1 protein depletion on STAT3 protein activation or on STAT3 target gene expression in three different liver cancer cell lines." (PMID 35267462, 2022). "In vitro, disruption of Stat5a, but not Stat1, which exhibited a positive correlation with cGAS regardless of TET2 expression, impaired Cgas expression in liver cancer cells." (PMID 38177099, 2024).
periodontitis (18 papers, 2019 to 2025). An acute or chronic inflammatory process that affects the tissues that surround and support the teeth. "STAT1 regulates immune and inflammatory responses, and its activation is associated with accelerated tissue damage in periodontitis." (PMID 41009706, 2025). "Studies have suggested that variations in the STAT-1 gene can influence susceptibility to periodontitis, as STAT-1 plays a role in the host's defense against bacterial invasion and inflammation." (PMID 39376880, 2024). "Wei and colleagues showed that activation of STAT1 pathway was linked with endothelial nitric oxide synthase gene knockout‐related (Nos3‐/‐) mouse model of periodontitis." (PMID 39436204, 2024). "STAT-1 mutations can cause infections like periodontitis, a chronic inflammatory disease affecting gum tissue and bone." (PMID 39376880, 2024). "It is known that STAT-1 mutations can cause common infections, such as periodontitis." (PMID 39376880, 2024). "Additionally, STAT1 has been shown to mediate hypertension associated with periodontitis bone resorption." (PMID 33448153, 2021). "A lncRNA antisense non-coding RNA in the INK4 locus (ANRIL), the first reported genetic risk factor for aggressive periodontitis, mediated the inflammatory response through the signal transducer and activator of transcription 1-alpha/beta (STAT1) signaling pathway." (PMID 32411181, 2020). "In periodontitis patients, a reduced expression of the STAT1 gene has been observed, which diminishes IFN-I activation and leads to increased periodontal inflammation." (PMID 39669221, 2025). "In patients with periodontitis, reduced STAT1 gene expression impairs downstream IFN-I signaling, leading to diminished IFN-I activation and excessive periodontal inflammation." (PMID 39669221, 2025). "By integrating these results with Gene Ontology, pathway, and disease enrichment analyses, it was determined that ESR1, MMP2, MMP9, MMP13, and STAT1 are potential key targets of EGCG in the context of periodontitis treatment." (PMID 41009706, 2025). "One previous study reveals that STAT-1 is crucial in Nitric oxide synthase-3 (Nos-3) related hypertension and worsened periodontitis." (PMID 39376880, 2024). "Our data corroborates with the earlier published reports demonstrating a role of higher expression and activation of STAT1 in periodontitis patients." (PMID 39436204, 2024). "Treatment with STAT1 inhibitor results in amelioration of bone resorption and periodontal destruction in periodontitis lesions in vivo." (PMID 39436204, 2024). "Here, we report that STAT1 expression is augmented in a mouse model of periodontitis with hypertension, and this results in upregulation of inflammatory and fibrosis genes, which aggravate hypertensive renal injuries." (PMID 33448153, 2021). "In conclusion, our research demonstrated that STAT1 expression was augmented by periodontitis, resulting in the upregulation of inflammatory and fibrosis genes, which aggravated the hypertensive renal injuries in a mouse model." (PMID 33448153, 2021). "While STAT1 expression was completely inhibited in all groups, it was dramatically decreased in hypertensive mice with periodontitis." (PMID 33448153, 2021). "In summary, we developed a Lipo-RSV system to treat periodontitis by modulating p-STAT1 and p-STAT3 to reprogram the macrophages from M1- to M2-like phenotype." (PMID 34930286, 2021). "Periodontitis aggravated kidney injury in hypertensive mice, and upregulation of STAT1 was observed when both periodontitis and hypertension were present; furthermore, STAT1 inhibitor moderated this effect." (PMID 33448153, 2021). "Expression of STAT1 was also upregulated in periodontal tissues during the early development stage of experimental periodontitis in rats." (PMID 33448153, 2021). "IHC and western blot results revealed that the abundance of STAT1‐positive cells increased in the presence of periodontitis or hypertension." (PMID 33448153, 2021).
periodontitis (continued). "The proportion of STAT1‐positive cells was highest when hypertension and periodontitis coexisted (PH), and the proportion decreased significantly in the inhibitor group (PHI)." (PMID 33448153, 2021). "The mechanism responsible for STAT1 expression in periodontitis and hypertension‐related renal injury was explored by detecting changes in STAT1 levels and the expression of inflammation and fibrosis‐related genes in mouse kidney tissues." (PMID 33448153, 2021). "Periodontitis augmented the expression of inflammatory and fibrosis genes by upregulating the expression of STAT1, thereby aggravating kidney injury in the hypertensive mouse model." (PMID 33448153, 2021). "Studies have shown that patients with invasive and chronic periodontitis express higher STAT1 levels than those in healthy individuals." (PMID 33448153, 2021). "Interestingly, in patients with T2DM who are known to have a higher susceptibility to periodontitis, we observed a heterogenous reprogramming of circulating intermediate and non-classical monocytes toward M1 transcription activation, including an increase in STAT1, IRF1 in intermediate monocytes." (PMID 32210958, 2020). "However, further research is needed to fully understand the relationship between periodontitis and STAT-1." (PMID 39376880, 2024). "Therefore, inhibition of STAT1 phosphorylation by curcumin contributes to the improvement of periodontitis conditions by inhibiting several cytokines, resulting in a reduction in inflammatory conditions in periodontal tissue." (PMID 39912085, 2024). "The analysis of gingival tissue samples from patients with DS and periodontitis showed attenuated expression of signal transducer and activator of transcription 1 (STAT1) and IFN regulatory factor 1 (IRF1) genes, confirming an altered activation of IFN signaling." (PMID 34200970, 2021). "Thus, we administered fludarabine to investigate the role of STAT1 in the aggravation of periodontitis‐induced renal damage in hypertensive mice." (PMID 33448153, 2021). "Here, we investigated whether STAT1 regulates periodontitis‐mediated aggravation of kidney injury with accompanying hypertension." (PMID 33448153, 2021). "However, the specific mechanism underlying STAT1 expression in periodontitis and hypertensive renal injury has not been reported." (PMID 33448153, 2021). "The strong interactions of EGCG with ESR1, MMP2, MMP9, MMP13, and STAT1 support its potential to modulate MMP activity and reduce extracellular matrix degradation, thereby mitigating tissue destruction in periodontitis." (PMID 41009706, 2025). "Protein–protein interaction (PPI) network analysis identified ESR1, MMP2, MMP9, MMP13, and STAT1 as hub genes, highlighting their central role in EGCG-mediated modulation of periodontitis." (PMID 41009706, 2025). "Recent evidence highlights several molecular mediators involved in the pathogenesis of periodontitis namely estrogen receptor 1 (ESR1), matrix metalloproteinases (MMP2, MMP9, MMP13), and signal transducer and activator of transcription 1 (STAT1)." (PMID 41009706, 2025). "To investigate the mechanisms involved in the protective effects of Pros1 against periodontitis in rats, we evaluated rat periodontal SOCS1/3 and STAT1/3 by Western blot analysis." (PMID 30729671, 2019). "Likewise, lower expression of STAT1 (p < 0.02) and interferon regulatory factor 1 (IRF1) (p < 0.01) was identified compared to euploid controls with periodontitis." (PMID 41462866, 2025). "Interestingly, higher levels of all the M1 markers STAT1 (r = .75; p < 0.0001), miR‐155 (r = .8; p < 0.0001), TNF‐α (r = .75; p < 0.0001), and CXCL10 (r = .62; p < 0.001) correlated with PPD in the periodontitis group." (PMID 39436204, 2024). "Our in vitro data align with this, showing IFN-γ pathway activation (IRF8, STAT1, IL-1β) during macrophage polarization under P. gingivalis infection, suggesting a positive link between RANKL and IFN-γ in regulating osteoclast differentiation in periodontitis." (PMID 39595193, 2024).
periodontitis (continued). "These pathways included the fibrosis pathway, which may initiate periodontitis and sicca-like symptoms through the upregulation of TNFSF13B, PML and STAT1." (PMID 35236379, 2022).
renal cell carcinoma (18 papers, 2002 to 2025). "As a result, five aging-related genes (DUSP22, MAPK14, MAPKAPK3, STAT1, and VCP) in normal tissues were found to be significantly associated with a worse survival outcome in patients with renal cell carcinoma (RCC)." (PMID 34207247, 2021). "Most recently it was demonstrated that suppression of Stat1 leads to radiosensitisation in renal cell carcinoma, which is consistent with our previous observations." (PMID 19437244, 2009). "For example, in renal cell carcinoma, activation of the self-ligand SLAMF7 immune receptor on T cells induces STAT1 and STAT3 phosphorylation and the expression of multiple inhibitory receptors and transcription factors associated with T-cell exhaustion." (PMID 40646691, 2025). "Fludarabine was previously found to inhibit STAT1 phosphorylation in stimulated PBMC and in smooth muscle cells as well as in renal cell carcinoma." (PMID 24911872, 2014). "Several studies described defects in different components of the IL-2R signaling pathway, resulting in decreased T cell proliferation, such as the absence of CD25 expression, impaired STAT1 and STAT5 activation or soluble products released from renal cell carcinoma that suppress JAK3." (PMID 29342108, 2018).
squamous cell carcinoma (18 papers, 2009 to 2025). A carcinoma arising from squamous epithelial cells. "This phenomenon was observed after STAT1 expression in a human squamous carcinoma cell line and type I interferon treatment of murine L-929 cells, human Daudi lymphoblastoid cells and isolated CD4+ lymphocytes from MS patients." (PMID 31817188, 2019). "One previous study has shown that reduced STAT1 expression in squamous cell carcinoma of the head and neck is due to gene methylation and silencing of the STAT1 gene." (PMID 29855346, 2018). "The later studies were performed using squamous carcinoma cells where the expression of STAT1 was ablated using STAT1 shRNA." (PMID 26689548, 2015). "Along these lines, STAT1-57 genes were induced in skin biopsies of conditions characterized by heightened proliferation, such as within wound margins, squamous cell carcinoma, basal cell carcinoma and actinic keratosis." (PMID 24260178, 2013). "To this end, we generated a stable STAT1 knockdown (KD) in SCC61, a clinically derived squamous cell carcinoma cell line, and studied the effect of STAT1 KD on tumour growth and response to IR in vivo." (PMID 19891767, 2009). "We demonstrated that stable KD of STAT1 in the SCC61 human squamous cell carcinoma leads to growth suppression and radio sensitization of tumour xenografts." (PMID 19891767, 2009). "Moreover, there are also some reports claiming that STAT1 activation in squamous cell cancer of the oral cavity is a potential predictive marker of response to adjuvant chemotherapy." (PMID 32597160, 2020). "We generated a stable knockdown of STAT1 in the SCC61 human squamous cell carcinoma cell line, established tumour xenografts in athymic mice, and compared transcriptomic and proteomic profiles of STAT1 wild-type (WT) and knockdown (KD) untreated or irradiated (IR) tumours." (PMID 19891767, 2009).
ulcerative colitis (18 papers, 2010 to 2025). An inflammatory bowel disease involving the mucosal surface of the large intestine and rectum. "In fact, intestinal STAT1 activation associates with severity of inflammatory symptoms in ulcerative colitis and Crohn’s disease patients." (PMID 23382730, 2013). "In ulcerative colitis patients’ mucosal samples, and to a minor extent in those with Crohn’s disease (CD), increased STAT1 expression and activation were reported." (PMID 36497125, 2022). "In ulcerative colitis, NF-κB and STAT1 are frequently studied as important transcriptional factors that can control the expression of cytokines, and provoke immunological responses including inflammation in the intestinal tract." (PMID 36080669, 2022). "Previous studies of these components have shown that costunolide ameliorates acute lung injury via attenuating MAPK and improved acute ulcerative colitis in mice through inactivation of NF-κB, STAT1/3, and Akt." (PMID 33790692, 2021). "This is an interesting observation given that macrophages are cells of monocytic lineage, and phosphorylated (p) STAT1 was mainly detected in monocytic cells and neutrophils in the inflamed mucosa of ulcerative colitis patients." (PMID 20423518, 2010). "The gene ADH1C might lead the increasing production of proinflammatory mediators by decreasing its expressions in the ulcerative colitis colon through the activation of the STAT1/NF-κB signaling pathway." (PMID 36991484, 2023). "Increased protein expression of STAT1 has been seen in ulcerative colitis in humans." (PMID 35802574, 2022). "Interestingly, colonic tissue samples of patients with Crohn's disease demonstrated increased STAT1 phosphorylation levels and, compared to samples taken from ulcerative colitis patients, increased SOCS3 levels." (PMID 24710357, 2014).
Arthritis (17 papers, 2006 to 2025). Inflammation of a joint. "Moreover, in STAT-1-deficient mice, increased joint inflammation in zymosan-induced arthritis has been observed as well as increased susceptibility to experimental autoimmune encephalomyelitis; in addition, these mice overexpressed the myeline basic protein-specific T cell receptor." (PMID 16507120, 2006). "In murine models, STAT1 activities often reduce arthritis severity, whereas STAT3 regulates leukocyte recruitment and activation, synovial hyperplasia and joint erosion." (PMID 34618359, 2022). "In a similar line, Stat1−/− mice show exacerbated zymosan-induced arthritis, possibly due to reduced SOCS1 expression." (PMID 32670294, 2020). "Local delivery of these NPs into the joints decreased expression of STAT1, induced regression of established arthritis in the CIA model, and increased production of IL-10." (PMID 30626016, 2019). "For example, the STAT1/IFN I pathway and the IL17 induced pathway has been implicated to be regulated by ROS and to play a role in development of arthritis and Ps." (PMID 29467756, 2018). "Examination of the paws revealed reduced mRNA for STAT1 but increased mRNA for IL-10, an immunomodulatory cytokine for arthritis." (PMID 25561237, 2014). "In comparison to control mice (day 0), expression of STAT-1 was significantly elevated at day 1 of arthritis." (PMID 16507120, 2006). "These functions suggest a protective role for STAT-1 in arthritis, and this role is supported by elevated expression of the STAT-1 pro-apoptotic target gene caspase-1 in RA synovium." (PMID 16507120, 2006). "The STAT-1 decoy ODN had a clear therapeutic effect on AIA in C57BL/6 mice when injected intra-articularly 4 hours prior to induction of arthritis." (PMID 16507120, 2006). "The STAT-1 decoy ODN was injected intra-articularly four hours prior to arthritis induction to allow sufficient cellular uptake and maximize efficacy at the time of induction." (PMID 16507120, 2006). "The STAT-1 decoy ODN was injected intra-articularly in methylated bovine serum albumin (mBSA)-immunized mice 4 h before arthritis induction." (PMID 16507120, 2006). "The role of macrophages in STAT-1-mediated effects is also supported by the observation that STAT-1 phosphorylation in murine zymosan-induced arthritis occurred first after infiltration of mononuclear cells into the synovium." (PMID 16507120, 2006). "In contrast to the mutant form, treatment with specific STAT-1 decoy ODN resulted in a significant reduction of the total arthritis score in both investigated phases." (PMID 16507120, 2006). "The progression of arthritis in KO mice is related to the downregulation of STAT1 in the joints." (PMID 22830570, 2012). "Our experiments demonstrate that a single local application of a decoy ODN neutralizing the transcription factor STAT-1 effectively inhibits antigen-induced arthritis, most likely through attenuating the enhanced expression of CD40 and other effector molecules in macrophages." (PMID 16507120, 2006). "The beneficial effects of the STAT-1 decoy ODN in experimental arthritis presumably mediated in part by affecting CD40 signalling in macrophages may provide the basis for a novel treatment of human RA." (PMID 16507120, 2006). "The transcription factor STAT-1 (signal transducer and activator of transcription-1) plays a pivotal role in the expression of inflammatory gene products involved in the pathogenesis of arthritis such as various cytokines and the CD40/CD40 ligand (CD40/CD40L) receptor-ligand dyad." (PMID 16507120, 2006). "As CD40-CD40L interactions have been implicated in arthritis a reduction in CD40 expression due to STAT-1 decoy ODN application may explain the attenuated arthritic symptoms in our AIA model." (PMID 16507120, 2006).